OR2M3 (olfactory receptor family 2 subfamily M member 3)
Description:
Odorant receptor.
Synonyms: OR2M3P; OR2M6; OST003; OR1-54
Tractability: Antibody: UniProt places it where antibodies can reach, with medium confidence; UniProt predicts a signal peptide or a membrane-spanning region; its Gene Ontology location is reachable by antibodies, with medium confidence.
Gene: Protein-coding gene on chromosome 1 (248,197,265 to 248,212,925, forward strand). Ensembl gene ENSG00000228198.
Subcellular location: Cell membrane
Pathways (Reactome):
Sensory Perception: Expression and translocation of olfactory receptors
Gene Ontology:
Molecular function: olfactory receptor activity; G protein-coupled receptor activity
Biological process: detection of chemical stimulus involved in sensory perception of smell; G protein-coupled receptor signaling pathway
Cellular component: plasma membrane; membrane
Genetic constraint (gnomAD): Loss-of-function variants: 2 observed, 5.18 expected, observed/expected ratio (o/e) 0.39, 90% interval 0.16 to 1.21. That is too few expected variants to judge how well the gene tolerates losing a copy. Missense variants: 410 observed, 399.4 expected, observed/expected ratio (o/e) 1.03, 90% interval 0.95 to 1.11. Synonymous variants: 151 observed, 145.49 expected, observed/expected ratio (o/e) 1.04, 90% interval 0.91 to 1.19.
Homologues: Orthologues: chimpanzee OR2M3 (98% identical), dog OR2M9 (79% identical). Paralogues in human: OR2M5 (93% identical), OR2M2 (92% identical), OR2M7 (92% identical), OR2M4 (74% identical), OR2T33 (57% identical), OR2T8 (57% identical), OR2T12 (55% identical), OR2L3 (54% identical), OR2V1 (54% identical), OR2V2 (53% identical), OR2L8 (53% identical), OR2T2 (53% identical), and 80 more.
Diseases named in the same sentence as OR2M3 in open-access papers:
OR2M3 is named in the same sentence as 1 disease in open-access papers, as found by Europe PMC text mining. Sharing a sentence is not in itself a finding about the gene and the disease. The quoted sentences say what the papers report.
tumor (1 paper, 2020). "For example, OR8B8 and OR8H1 were exclusively detected in malignant breast epithelial cells, whereas OR1A1 and OR2M3 activation were observed in 11 and 10 different tumor types respectively, suggesting a distinct mode of expression regulation." (PMID 32917933, 2020).